DENND6A (DENN domain containing 6A)
Description:
Guanine nucleotide exchange factor (GEF) for RAB14. Component of an endocytic recycling pathway that is required for the control of ADAM10 transport, shedding of N-cadherin/CDH2 by ADAM9 or ADAM10 and regulation of cell-cell junctions. Required for RAB14 recruitment to recycling endosomes.
Synonyms: FAM116A; FLJ34969; AFI1A
Tractability: PROTAC: ubiquitination databases record sites on it; its protein half-life has been measured.
Gene: Protein-coding gene on chromosome 3 (57,625,454 to 57,693,127, reverse strand). Ensembl gene ENSG00000174839.
Subcellular location: Recycling endosome; Cytoplasm
Subcellular location (Human Protein Atlas): Vesicles
Pathways (Reactome):
Vesicle-mediated transport: RAB GEFs exchange GTP for GDP on RABs
Gene Ontology:
Molecular function: guanyl-nucleotide exchange factor activity; protein binding
Biological process: positive regulation of cell-cell adhesion mediated by cadherin
Cellular component: cytoplasm; recycling endosome; cytosol
Genetic constraint (gnomAD): Loss-of-function variants: 33 observed, 62.34 expected, observed/expected ratio (o/e) 0.53, 90% interval 0.4 to 0.71. The upper end of that interval is the gene's LOEUF score, 0.71, which puts it in group 2 of 6, group 1 being the genes least tolerant of losing a copy. Missense variants: 484 observed, 592.88 expected, observed/expected ratio (o/e) 0.82, 90% interval 0.76 to 0.88. Synonymous variants: 228 observed, 208.21 expected, observed/expected ratio (o/e) 1.1, 90% interval 0.98 to 1.22.
Homologues: Orthologues: chimpanzee DENND6A (99% identical), macaque DENND6A (99% identical), rabbit DENND6A (96% identical), dog DENND6A (96% identical), guinea pig DENND6A (95% identical), mouse Dennd6a (95% identical), rat Dennd6a (95% identical), pig DENND6A (91% identical), zebrafish dennd6aa (76% identical), tropical clawed frog dennd6a (75% identical), Drosophila melanogaster CG3309 (41% identical), Caenorhabditis elegans F53H1.3 (39% identical). Paralogues in human: DENND6B (56% identical).
Diseases named in the same sentence as DENND6A in open-access papers:
DENND6A is named in the same sentence as 1 disease in open-access papers, as found by Europe PMC text mining. Sharing a sentence is not in itself a finding about the gene and the disease. The quoted sentences say what the papers report.
cancer (1 paper, 2021). A tumor composed of atypical neoplastic, often pleomorphic cells that invade other tissues. "Genes such as PYGM, BMF, MBNL3, DENND6A, REEP5, KLF6 and ITM2C are potentially regulated by circYPEL2 and involved in cancer-specific pathways, which are needed to be validated in further studies." (PMID 35052380, 2021).